TIGIT (T cell immunoreceptor with Ig and ITIM domains)
Diseases named in the same sentence as TIGIT in open-access papers (continued):
Sharing a sentence is not in itself a finding about the gene and the disease.
tumor (continued). "Studies using lymph node biopsies performed on retrospective cohorts of heterogeneous FL patient populations receiving various treatments have suggested that the amount of intra-tumor effector T cells expressing ICP, in particular TIM3, PD-1 and TIGIT, could have a prognostic value." (PMID 31530876, 2019). "The impact of chronic TCR-A2 (self)-interactions on tumor-redirected A2pos CD8 T cells upon TCR transduction of increased affinities led to the co-expression of multiple inhibitory receptors such as PD-1, TIM-3, TIGIT and 2B4, that preceded T cell hyporesponsiveness." (PMID 31690351, 2019). "In addition, tumor-infiltrating NK cells from tumor patients with lymph node invasion expressed higher levels of TIGIT, compared with those from patients without lymph node invasion." (PMID 31552017, 2019). "These exhausted CD8+ T cells express co-inhibitory molecules (e.g., PD-1, LAG-3, TIM-3, TIGIT) and lose the ability to produce multiple cytokines such as interferon (IFN)-γ, tumor necrosis factor (TNF)-α, and interleukin (IL)-2, namely they lose anti-tumor activities." (PMID 30696484, 2019). "Initial ex vivo and murine studies targeting dual blockade of TIGIT and either PD-1 or TIM-3 has shown a synergistic effect in immune cell proliferation, cytokine release, degranulation, and reversal of T cell exhaustion with subsequent tumor rejection and induction of protective memory responses." (PMID 29544515, 2018). "Antibody-mediate TIGIT blockade could significantly inhibit tumor growth in MC38-bearing mice, but not in MC38-sgRNA1 bearing mice." (PMID 30555485, 2018). "Further, in BABL/c nude mice, CD8+ T cells depleting mice and NK cells depleting nude mice, the promotion of tumor growth was significantly diminished, suggesting that both NK cells and CD8+ T cells were involved in the tumor promoting process mediated by intrinsic TIGIT." (PMID 30555485, 2018). "Meanwhile, in BABL/c nude mouse model, TIGIT knockout could not entirely rescue tumor growth, suggesting that tumor-intrinsic TIGIT may suppress other anti-tumor immune cells (probably NK cells) independently of T cells." (PMID 30555485, 2018). "Interestingly, in our study, we also observed that the STAT3-blocked HCC vaccine could prevent tumor-induced exhaustion of CD8+ T and NK cells, as depicted by the downregulation of PD-1, TIGIT, and LAG-3 in HCC-vaccine-immunized mice." (PMID 29115974, 2017). "However, immunosuppressive tumor-associated macrophages (TAMs) remained prevalent and expressed ligands for alternative checkpoints such as CTLA-4 and TIGIT, suggesting that targeting these pathways may be necessary to overcome TAM-mediated suppression and improve anti-tumor immunity." (PMID 40960500, 2025). "Importantly, combining the epigenetic anti‐tumor drug GSK3326595 with CPT‐11 significantly upregulates the immune receptor tyrosine‐based inhibitory motif (TIGIT) level on CD8+ T cells and subsequently demonstrates impressive anti‐tumor efficacy in vivo when additional anti‐TIGIT is included." (PMID 40344511, 2025). "Additionally, the presence of a highly immunosuppressive Tumor microenvironment (TME), enriched with regulatory T cells (Tregs), myeloid-derived suppressor cells (MDSCs), and the upregulation of alternative inhibitory receptors like LAG-3, TIM-3, and TIGIT, further impedes anti-tumor immunity." (PMID 41584608, 2025). "Also, increased levels of markers such as TIGIT, Nrp-1, neurogenic locus notch-homolog protein 1 (Notch-1), T cell immunoglobulin and mucin domain 3 (TIM-3), B-lymphocyte-induced maturation protein 1 (BLIMP-1) and others also contribute to enhanced Treg activity and the promotion of tumor growth." (PMID 38891091, 2024). "TIGIT, which serves as the “braker” in immune checkpoint regulation, together with another “braker”, PD-1/PD-L1, may not be sufficient to activate the immune cells to kill tumor cells, especially in patients with advanced or high-burden tumors." (PMID 38229100, 2024).
tumor (continued). "While targeting of CD200, TIGIT, and LAG3 is less established in GBM treatment, these targets should be highly considered for future drug development as they appear to be present in GBM and may serve as a strong alternative target should a patient’s tumor express low amounts of PD-1/PD-L1 or CTLA4." (PMID 39409893, 2024). "Cell-cell interaction showed that the interaction between TIGIT on MCL cells and its ligand CD155 on CD16+ monocytes significantly increased after relapse, which might attenuate the ability of myeloid cells to present tumor antigens and lead to weaker antitumor immune surveillance." (PMID 37149643, 2023). "Furthermore, single cell RNA sequencing revealed a high heterogeneity of tumor infiltrating CD8+ T cells in CTCL skin with a strong variation in the expression of co-inhibitory receptors PD1, CTLA4, TIM3, LAG3, and TIGIT, which could affect capacity of tumor cell killing." (PMID 37691935, 2023). "In addition, TIGIT, which is a T-cell immune receptor with Ig and ITIM domains and was upregulated in the high-immunity, has been recently identified as an attractive cancer immunotherapy target, because of its key role in interactions between the cells within the tumor microenvironment." (PMID 35530341, 2022). "In addition, immune checkpoint-related molecules – PD-L1, CTLA-4, PD-1, and TIGIT – are more highly expressed in normal (but not tumor) lung tissues; these molecules might dampen immune response to either viruses or cancer." (PMID 36324736, 2022). "Results from this study suggested that patients with CRC may harbor tumor-infiltrating Tregs with a specific protein signature, including the co-stimulatory molecules (OX40, 4-1BB), cytokine receptors (IL1R2, IL21R, CCR8, CD30), and co-inhibitory molecules (PD-L1, TIGIT)." (PMID 33527196, 2021). "Univariate analysis showed that CD155 and TIGIT expression, T stage, lymph node and distant metastasis, TNM stage, and therapeutic strategy were all associated with OS, whereas sex, age, alcohol and smoking history, tumor location, tumor size, and Ki-67 score were not." (PMID 33490104, 2020). "Interestingly, TIGIT expressed on tumor-infiltrating effector cells synergizes with other co-inhibitory molecules to dampen the immune response and promote effector cells dysfunction, so that the co-blockade of TIGIT/PD-1/TIM-3 restored exhausted CD8+ T cells and induced complete tumor rejection." (PMID 32610578, 2020). "However, our study showed that tumor-intrinsic TIGIT did not inhibit the function of tumor cells, which may due to the TIGIT-PVR interaction did not result in any inhibitory consequences in vitro, or other unknown signals to compensate." (PMID 30555485, 2018). "To confirm whether TIGIT could be considered as the target for immunotherapy, we observed that TIGIT blockade using antibody or recombinant mouse PVR protein could also suppress tumor growth, augment tumor-infiltrating lymphocytes and boost anti-tumor immune response in CT26 mice model." (PMID 30555485, 2018). "Moreover, we observed statistically significant correlations between PD-1 and TIGIT expression in CD4+ T cells in AEM (r = 0.4769, p = 0.0159) and tumor tissues (r = 0.5121, p = 0.0089), and in CD8+ T cells in PBMC (r = 0.3888, p = 0.0210) and tumor tissues (r = 0.4793, p = 0.0153)." (PMID 27577071, 2016). "IPI-549 or PD-L1 single or dual treatments did not affect PD-1, CTLA-4, TIGIT, LAG-3, or TIM-3 expression in tumor-infiltrating CD4+ T-cells in HNSCC tumor-bearing mice." (PMID 41431358, 2026). "Single cell RNAseq analysis of tumor infiltrating CD8 T cells shows positive correlation of CTLA-4, TIM-3, LAG-3, TIGIT, GITR, 4-1BB, and OX40 with PD-1 but negative correlation of KLRG1 with PD-1." (PMID 39832302, 2025). "The stability of inhibitory markers, including PD-1, KIR2D, and TIGIT, suggests that BaEV CAR γδ T cells are not more prone to exhaustion and maintain a robust anti-tumor potential." (PMID 40547029, 2025).
tumor (continued). "Subsequently, we compared the expression of exhaustion related molecules in CD4+T cells and found that CD4+T cells in obese tumor samples had higher expression of TIGIT and CTLA4 molecules compared with non-obese tumor samples." (PMID 38311726, 2024). "The binding of PVRL2 to TIGIT is much weaker than that of PVR to TIGIT, suggesting that it does not play a significant role in the tumor immune system." (PMID 39156900, 2024). "We observed a similar result by flow cytometry, with anti-PD-L1 + anti-TIGIT treatment, but not anti-PD-L1 + anti-TIGIT + anti-CSF-1R treatment, driving a reduced expression of TOX in tumour CD8+ T cells." (PMID 38418879, 2024). "In contrast to other immune checkpoint receptors, TIGIT was not expressed on ILCs, which, however, more frequently expressed CD39 toward the tumor center." (PMID 37448786, 2023). "Double positive (TIGIT+CTLA-4+) (IR-9) and triple positive (TIGIT+CTLA-4+TIM-3+) (IR-12) were highest among PD1+CD28+ T cells in periphery and did not increase in the tumor." (PMID 37898752, 2023). "To determine the role of DCs in RT combined with anti-TIGIT therapy, we first measured the expression of CD155 on DCs in TdLNs and non-TdLNs from a tumor mouse model and normal-LNs from healthy mice using flow cytometry." (PMID 35794399, 2023). "CD274 expression was found to be down-regulated in tumor tissues (P < 0.05), while TIGIT, PDCD1, CTLA4 and LAG3 expression in tumor tissues were not statistically different." (PMID 36959799, 2023). "There are two ligands binding TIGIT: the nectin family CD155 and CD112, which are expressed on APCs, T cells, and a variety of non-hematopoietic tumor cells." (PMID 37691932, 2023). "In this study, the anti-PD-1 antibody not only did not inhibit tumor growth, but it also led to the mice harboring many more T cells expressing PD-1, LAG-3, and TIGIT compared to the non-treatment mice." (PMID 37999131, 2023). "The anti-MSLN CAR-T cells showed signs of tumor recurrence in the late stage of the experiment, while the MT CAR-T cells and anti-MSLN CAR-T ± anti-α-TIGIT mice showed no tumor recurrence." (PMID 37359558, 2023). "One study found that TIGIT is particularly abundant on TILs and explicitly identifies the most nonfunctional CD8+ T-cells and FOXP3+ Tregs in mouse tumor tissue." (PMID 37835436, 2023). "Although PD-1 and TIGIT are thought to regulate different costimulatory receptors (CD28 and CD226), effectiveness of PD-1 or TIGIT inhibition in preclinical tumor models was reduced in the absence of CD226." (PMID 35263569, 2022). "Both anti-TIGIT and anti-PD-L1 agents were subsequently tested in a mouse model of CRC, where neither monotherapy managed to have a significant effect on tumor growth and survival." (PMID 35327475, 2022). "As for T cell exhaustion, notable negative relationship between FXYD2 expression and CTLA-4, TIGIT, and BTLA persisted before and after tumor purity adjustment." (PMID 36313180, 2022). "In contrast to the findings in normal lung tissue from our NSCLC patients, when we examined tumor tissue in this cohort, ACE2 expression did not correlate with levels of PD-L1, ICOS, CTLA-4, PD-1, and TIGIT." (PMID 36324736, 2022). "We found that besides TNFRSF4, Treg functional signature genes such as FoxP3, CTLA4, TIGIT, TNFRSF18 (GIRT), CCR8, LAYN, and MAGEH1 were also overexpressed in C11-Tregs-FoxP3 of treatment-naive and non-MPR tumor lesions, but not for MPR tumor lesions." (PMID 35831283, 2022). "Although MTD OX reduced tumor growth and increased overall survival in CT26-bearing mice, as expected, it failed to synergize with anti-TIGIT therapy." (PMID 36389751, 2022). "They expressed, for the most part, TIGIT, but did not express CTLA-4, which was expressed by PD-1hiCD39+ CD4 T cells at the tumor site." (PMID 35954341, 2022).
tumor (continued). "ROC1 tumors failed to respond to treatment with antibodies against PD-1 and TIGIT, confirming that ROC1 is a cold tumor lacking immune cell infiltration and immune checkpoint expression and thus a good model of ICI-resistant disease." (PMID 35902768, 2022). "A unique property of TIGIT among inhibitory immune checkpoints is that its blockade not only augments anti-tumor effector CD8+ T-cell responses, but also anti-tumor NK-cell responses, and reduces the suppressive capacity of regulatory T cells." (PMID 34367161, 2021). "Blockage of CD226 completely abrogated the effect of TIGIT/PD-L1 in the tumor but did not impact IFN-γ-producing CD8+ T cell frequency in the tumor-draining lymph node, suggesting a unique interplay among CD226, TIGIT and PD-1 in the tumor microenvironment." (PMID 34417435, 2021). "TIGIT can bind to the receptors CD155 (poliovirus receptor-PVR), CD112 (PVRL2, nectin-2), and CD113 (Nectin-3) in immune cells, non-immune cells, and tumor cells, resulting in T cell activation and suppression of cytotoxicity." (PMID 34631507, 2021). "TIGIT is expressed on around 20% of intra-tumoral Th in HCC patients, but not over-expressed compared to Th in tumor-free liver tissue and in the circulation." (PMID 34367161, 2021). "Since F. nucleatum only activates human TIGIT and CEACAM1 and not their murine homologs, tumor acceleration in the mouse models used here cannot involve impaired T cell and NK cell killing-activity via the activation of these important checkpoints." (PMID 32591509, 2020). "Indeed, targeting NK cell checkpoint receptors using anti-TIGIT and anti-NKG2A mAbs could restore the anti-tumor efficacy of both NK and T cells, and more significantly, that anti-tumor capacity could be amplified using a combination with anti-PD-1/PD-L1 mAbs in various tumor models." (PMID 32714324, 2020). "TIGIT binds to CD155 and CD112 that are expressed by antigen-presenting cells (APCs), T cells and other non-hematopoietic cells, including tumor cells." (PMID 33101304, 2020). "Values of few populations (CD45RO+ in Frozen PBMC, and CD45+, CD3+TIGIT+, CD3+CTLA4+, and CD3+CD28+ in tumor biopsies) did not give rise to statistically equivalent results using equivalence test." (PMID 31165047, 2019). "Interestingly, except that TIGIT was reported to be expressed on NK and T cells, the expression of PVR was also observed on CD4+ T cells, CD8+ T cells and NK cells, indicating the function of these cells might be suppressed by TIGIT on tumor cells via interaction with PVR." (PMID 30555485, 2018). "In our cohort, TIGIT and CD155 protein levels were quantified in tissue homogenates using an ELISA-based approach, providing a measure of their overall abundance within the tumor compartment rather than cell-type-specific or spatially resolved expression." (PMID 41596586, 2026). "The results revealed a significant increase in NK cell-mediated tumor cell killing following MS-275 treatment, with NKG2A blockade by monalizumab further enhancing this effect; however, no additional benefit was observed with TIGIT blockade by tiragolumab." (PMID 40296045, 2025). "Compared to non-IBC, HER2+ IBC tumour cells engaged CD8+ T cells through the MIF–CD74 ligand–receptor axis, while CD8+ T cells specifically upregulated immune checkpoint molecules LAG3 and TIGIT." (PMID 40624675, 2025). "In the B16F10 and STOSE models, where blocking FGL2 did not prolong survival, increased presence of TIGIT+ Tregs, which do express high amounts of FGL227, may have impeded tumour elimination." (PMID 38191799, 2024). "However, TIGIT + CD4 + T cells and TIGIT + CD56 + NK cells rates in pre-treatment tumor were not statistically significantly correlated with TRG (p > 0.05)." (PMID 35794399, 2023). "TIGIT acts as an inhibitor receptor when binding to its ligands PVR, nectin-2, and nectin-3 (CD113), all of which are expressed in APCs and a variety of non-hematopoietic cells, including tumor cells." (PMID 35164813, 2022).
tumor (continued). "Tumor-infiltrating CD4+ T cells showed significantly elevated expression of PD-1 (NT; 32.5 ± 2.0 vs. TT; 46.3 ± 2.7), TIM-3 (NT; 2.7 ± 0.3 vs. TT; 10.8 ± 1.3) and TIGIT (NT; 26.5 ± 1.8 vs. TT; 37.0 ± 2.1), but not LAG-3." (PMID 33477864, 2021). "Nevertheless, such MSI+ CYT-high tumor cells are not effectively eliminated by the immune system, due to the increased levels of several immune-inhibitory checkpoint molecules, such as PD-L1, PD-L2, CTLA-4, LAG3, TIGIT, IDO1 and VISTA." (PMID 31429779, 2019). "Interestingly, TIGIT expression levels in peripheral blood and tumor tissues in patients with primary breast cancer (PBC) seem to be related to the age of the patient, but not the tumor size or lymph node metastasis." (PMID 40890162, 2025). "We also found that the expression levels of TIGIT on CD8 + T cells, CD4 + T cells and NK cells in TILs and TDLNs treated with RT were statistically significantly higher than expression levels on cells not treated with RT in LLC and B16 tumor-bearing mouse models." (PMID 35794399, 2023). "In the secondary tumors, we also found a higher frequency of tumor-infiltrating CD8 + T cells in the TILs and a higher frequency of CD8 + T cells expressing TNF-α and IFN-γ in the combination treatment group than in the individual anti-TIGIT or RT groups (data not shown)." (PMID 35794399, 2023). "Unlike the case in these BA-relapsed patients, TIGIT did not appear to be expressed in MCL tumor cells in the BA-refractory patient (R); in contrast, elevated expression of other checkpoint molecules, LAGLS9 and CYBB, was detected in MCL tumor cells from patient R." (PMID 36163179, 2022). "PD-1, CTLA4, LAG3, TIGIT, and TIM-3 (HAVCR2) are known as inhibitory molecules expressed in exhausted T cells that have an impaired ability to kill tumors because they neither respond to T cell receptor stimulation nor secrete anti-tumor cytokines such as interferon γ and tumor necrosis factor-α." (PMID 35480109, 2022). "Besides, TIGIT blockade could significantly increase the percentage and IFN-γ production of tumor infiltrating CD8+ T cells along with tumor inhibition in MC38 but not in MC38-sgRNA1 bearing mice." (PMID 30555485, 2018). "First, the TIGIT interaction with PVR is of a much higher affinity compared to the TIGIT interaction with CD112, participating in the negative regulation of activated T cells and NK cells by up-regulating IL-10 expression and down-regulating IL-12 expression in tumor cells or APCs." (PMID 29735917, 2018).